ENSG00000258472 (novel protein)
Gene: Protein-coding gene on chromosome 17 (28,580,012 to 28,614,185, reverse strand). Ensembl gene ENSG00000258472.
Genetic constraint (gnomAD): Loss-of-function variants: 31 observed, 43.38 expected, observed/expected ratio (o/e) 0.71, 90% interval 0.54 to 0.96. Missense variants: 369 observed, 410.32 expected, observed/expected ratio (o/e) 0.9, 90% interval 0.82 to 0.98. Synonymous variants: 144 observed, 162.91 expected, observed/expected ratio (o/e) 0.88, 90% interval 0.77 to 1.01.